CLMN (calmin)
Synonyms: KIAA1188; FLJ12383; KIAA0500
Tractability: Antibody: UniProt predicts a signal peptide or a membrane-spanning region. PROTAC: its protein half-life has been measured.
Gene: Protein-coding gene on chromosome 14 (95,181,940 to 95,319,921, reverse strand). Ensembl gene ENSG00000165959.
Subcellular location: Membrane
Subcellular location (Human Protein Atlas): Nuclear bodies; Cytosol
Gene Ontology:
Molecular function: actin filament binding
Biological process: negative regulation of cell population proliferation; nuclear migration
Cellular component: cytoplasm; meiotic nuclear membrane microtubule tethering complex; nuclear outer membrane; membrane
Genetic constraint (gnomAD): Loss-of-function variants: 54 observed, 89.69 expected, observed/expected ratio (o/e) 0.6, 90% interval 0.48 to 0.75. The upper end of that interval is the gene's LOEUF score, 0.75, which puts it in group 3 of 6, group 1 being the genes least tolerant of losing a copy. Missense variants: 1,143 observed, 1,271 expected, observed/expected ratio (o/e) 0.9, 90% interval 0.86 to 0.94. Synonymous variants: 463 observed, 486.34 expected, observed/expected ratio (o/e) 0.95, 90% interval 0.88 to 1.03.
Homologues: Orthologues: chimpanzee CLMN (99% identical), macaque CLMN (89% identical), pig CLMN (73% identical), mouse Clmn (72% identical), dog CLMN (71% identical), guinea pig CLMN (68% identical), rat Clmn (67% identical), rabbit CLMN (59% identical), tropical clawed frog CLMN (35% identical), zebrafish clmna (28% identical), zebrafish clmnb (21% identical). Paralogues in human: SYNE1 (22% identical), PLEC (21% identical), SYNE2 (21% identical), DST (20% identical), MACF1 (20% identical), SPTBN1 (19% identical), DMD (19% identical), SPTBN4 (18% identical), UTRN (18% identical), SPTB (18% identical), SPTBN2 (18% identical), FLNA (16% identical), and 24 more.
Diseases named in the same sentence as CLMN in open-access papers:
CLMN is named in the same sentence as 6 diseases in open-access papers, as found by Europe PMC text mining. Sharing a sentence is not in itself a finding about the gene and the disease. The quoted sentences say what the papers report.
breast carcinoma (3 papers, 2013 to 2023). "For example, two studies that profiled gene expression in response to 1,25D treatment of breast cancer explants in culture, which were primarily ER+ ductal carcinomas, revealed only four commonly regulated genes (CYP24A1, CLMN, EFTUD1, SERPINB1)." (PMID 34950835, 2021).
neuroblastoma (1 paper, 2022). Neuroblastoma (NB) is the most common solid, extracranial childhood tumor. "In addition, E-protein promotes calmin (CLMN), its overexpression alone is sufficient to inhibit neuroblastoma (N2A) cell proliferation, and one GWA study strongly associated the CLMN gene with the reduction in the total cholesterol levels after statin treatment." (PMID 35723340, 2022).
psoriasis (1 paper, 2015). An autoimmune condition characterized by red, well-delineated plaques with silvery scales that are usually on the extensor surfaces and scalp. "Furthermore, SNPs in CLMN (rs2282276) and CCL4L (rs1634517) have not been associated with psoriasis or age at onset." (PMID 26613086, 2015).
CLMN also shares sentences with these, for which no sentence is quoted: breast tumors (1 paper); head and neck tumours (1); tumours (1).